GLP1R (glucagon like peptide 1 receptor)
Diseases named in the same sentence as GLP1R in open-access papers (continued):
Sharing a sentence is not in itself a finding about the gene and the disease.
type 2 diabetes (continued). "The addition of GCGR agonism to GLP-1R agonism may therefore prove to be more efficacious in the treatment of type 2 diabetes and obesity, producing additive effects on energy intake and expenditure." (PMID 38095657, 2024). "There is presently far less information available about how lipid modification of GIPR agonists alters GIPR function or interactions with membrane lipids, probably as a result of the relatively recent interest in GIPR as a therapeutic target in type 2 diabetes and obesity compared to the GLP-1R." (PMID 38614123, 2024). "Multivariable Mendelian randomization analyses that were corrected for overdispersion heterogeneity suggest that bodyweight lowering rather than type 2 diabetes liability lowering effects of GLP1R agonism are more likely contributing to reduced CAD risk." (PMID 38379245, 2024). "The guidelines of the American Diabetes Association and European Association for the Study of Diabetes suggest that patients with obesity type 2 diabetics and chronic kidney disease need either glucagon-like peptide 1 receptor analogues or sodium-glucose cotransporter-2 inhibitors." (PMID 38365744, 2024). "Given that GLP-1R agonists are presently employed in treating type 2 diabetes, their application for testing in VCID and AD could be swiftly implemented." (PMID 38659577, 2024). "Furthermore, aberrant Mfn2 expression has been reported in metabolic disorders, including type 2 diabetes mellitus and insulin resistance, for which Exenatide and GLP-1R agonists are effective in treatments." (PMID 38627765, 2024). "A variety of GLP‐1R agonists have been developed to treat type 2 diabetes mellitus." (PMID 38926763, 2024). "Long-acting glucagon like peptide-1 receptor agonists, such as dulaglitide and semaglutide, not only reduce glycosylated hemoglobin levels, but also significantly improve BMI in overweight or obese patients with type 2 diabetes." (PMID 39121301, 2024). "We aimed to use the recently developed Bayesian causal forest (BCF) method to develop and validate an individualised treatment selection algorithm for two major type 2 diabetes drug classes, sodium–glucose cotransporter 2 inhibitors (SGLT2i) and glucagon-like peptide-1 receptor agonists (GLP1-RA)." (PMID 38388753, 2024). "Semaglutide is a glucagon-like peptide-1 receptor agonist that improves glycemic control and reduces cardiovascular outcomes in type 2 diabetes (T2D) by several mechanisms including enhanced β–cell response, postponed gastric emptying, inhibition of glucagon secretion, and weight-loss." (PMID 39696569, 2024). "In addition to semaglutide, other GLP-1R agonists now approved for the treatment of type 2 diabetes have been investigated in combination with background metformin therapy." (PMID 38095657, 2024). "Minority racial and ethnic populations have the highest prevalence of type 2 diabetes mellitus but lower use of sodium-glucose co-transporter-2 inhibitors (SGLT2i) and glucagon-like peptide-1 receptor agonists (GLP1ra), novel medications that reduce morbidity and mortality." (PMID 39085578, 2024). "However, as obesity and type 2 diabetes worsen, glucose-dependent insulinotropic polypeptide loses its insulinotropic efficacy, whereas GLP-1 receptor (GLP-1R) agonists continue to be effective owing to its signaling switch from Gs to Gq." (PMID 38376482, 2024). "Current stratification in type 2 diabetes treatment guidelines involves preferential prescribing of two major drug classes, sodium–glucose cotransporter 2 inhibitors (SGLT2i) and glucagon-like peptide-1 receptor agonists (GLP1-RA), to subgroups of people with or at high risk of cardiorenal disease." (PMID 38388753, 2024). "Therefore, development of incretin dual agonists such as the novel GCGR/GLP-1R dual agonist survodutide is an important step towards the more effective treatment of people with type 2 diabetes and obesity." (PMID 38095657, 2024). "GLP-1R agonists are used to treat type 2 diabetes and obesity." (PMID 39339176, 2024).
type 2 diabetes (continued). "Background and Objectives: Limited evidence exists regarding the safety and efficacy of glucagon-like peptide-1 receptor agonists (GLP-1RAs) in type 2 diabetes mellitus (T2DM) patients with advanced chronic kidney disease (CKD) or end-stage kidney disease (ESKD)." (PMID 38248365, 2024). "Furthermore, GLP-1 receptor (GLP-1R) agonists are widely used for treating Type 2 diabetes due to their ability to enhance glucose-dependent insulin secretion, reduce glucagon levels, and minimize the risk of hypoglycemia." (PMID 39582948, 2024). "GLP-1R is located in multiple tissues in the human body such as pancreatic islets, heart, intestine, kidney and brain and represents an established target for the treatment of type 2 diabetes mellitus." (PMID 36769142, 2023). "The current study aimed to develop long-acting protease-resistant GLP-1R agonists with the potential for administration in type 2 diabetes mellitus treatment by designing and computationally analyzing the fusion proteins of the native or protease-resistant mutant GLP-1 and an HSA-binding DARPin." (PMID 37853095, 2023). "The most common keywords used in the most recent and most cited research papers are semaglutide, obesity, diabetes mellitus type 2, glucagon-like peptide-1, glucagon-like peptide-1 receptor agonist, antidiabetic agent, liraglutide, and cardiovascular disease (CVD)." (PMID 37808605, 2023). "This cohort study assesses the risk of fractures associated with sodium-glucose cotransporter 2 inhibitors vs incretin-based drugs of dipeptidyl-peptidase 4 inhibitors and glucagon-like peptide 1 receptor agonists, separately, in postmenopausal individuals with type 2 diabetes." (PMID 37751205, 2023). "Glucagon-like peptide-1 receptor (GLP-1R) agonists are currently utilized in the treatment of type II diabetes and obesity but may play a role in the treatment of IIMs." (PMID 38292961, 2023). "Patients with type 2 diabetes (T2D) treated with glucagon-like peptide-1 receptor agonists may experience reductions in weight and blood pressure." (PMID 36894938, 2023). "However, studies assessing the effects of the combination of semaglutide, an FDA-approved GLP-1R agonist for diabetes type II, and varenicline or bupropion to reduce alcohol intake in male and female rats remains to be conducted." (PMID 37719854, 2023). "Liraglutide, a glucagon-like peptide-1 receptor agonist (GLP1-RA) already approved for the treatment of type 2 diabetes has been recently introduced at the dosage of 3 mg for obese subjects with associated comorbidities such as hypertension, dyslipidemia and obstructive sleep apnea syndrome." (PMID 36993998, 2023). "Though clinical trial data support the efficacy of dual GIPR/GLP1R agonism for glycemic control in type 2 diabetes, it is unclear whether pharmacological GIPR agonism alone would confer similar favorable effects on glucose metabolism." (PMID 37250804, 2023). "For this reason, GLP1 receptor (GLP1R) agonists are widely used in patients with type 2 diabetes." (PMID 37379656, 2023). "Agonism at the receptor for the glucose-dependent insulinotropic polypeptide (GIPR) is a key component of the novel unimolecular GIPR:GLP-1R co-agonists, which are among the most promising drugs in clinical development for the treatment of obesity and type 2 diabetes." (PMID 37592302, 2023). "Whether glucagon-induced insulin secretion mediated via the GLP1R occurs to a greater extent in type 2 diabetes is unknown." (PMID 37751301, 2023). "GLP-1R agonists are hence approved as treatment of diabetes type II." (PMID 37719854, 2023). "Consequently, these observations have led to diabetes therapy development in the form of GLP-1 receptor (GLP-1R) agonists for the treatment of type 2 diabetes mellitus and, subsequently, for obesity." (PMID 36975599, 2023).
type 2 diabetes (continued). "Combined glucose-dependent insulinotropic polypeptide receptor (GIPR) and glucagon-like peptide-1 receptor (GLP1R) agonism is superior to single GLP1R agonism with respect to glycemic control and weight loss in obese patients with or without type 2 diabetes." (PMID 37379656, 2023). "The glucagon-like peptide-1 receptor (GLP-1R) is a major type 2 diabetes therapeutic target." (PMID 37134170, 2023). "Efficacy and tolerability of tirzepatide, a dual glucose-dependent insulinotropic peptide and glucagon-like peptide-1 receptor agonist in patients with type 2 diabetes: A 12-week, randomized, double-blind, placebo-controlled study to evaluate different dose-escalation regimens." (PMID 37908927, 2023). "Our study found that the serum Wnt5a protein level of newly diagnosed type 2 diabetes patients was significantly increased after the intervention of the glucagon-like peptide-1 receptor agonist compared with before treatment, and the antagonist Sfrp5 was lower than that of the control group." (PMID 37255814, 2023). "Nevertheless, most of the reports on the improvement of the lipid profile, including modest reductions in LDL-C, total cholesterol, and triglycerides, come from clinical trials of GLP-1R agonists in patients with type 2 diabetes and the observed effects were exerted by exogenous, long-acting GLP-1." (PMID 36010335, 2022). "The effects of GLP-1R activation are useful in the management of type 2 diabetes mellitus (T2DM)." (PMID 36293281, 2022). "Therefore, GLP-1R agonist (GLP-1RA) is used in patients with type 2 diabetes as an antidiabetic agent." (PMID 35524186, 2022). "The continuing clinical successes of GLP-1 receptor (GLP-1R) agonists has reinforced the substantial potential of this pharmaceutical approach to the treatment of type 2 diabetes and obesity, and these agonists remain the only class of pharmaceuticals approved for both indications." (PMID 35809773, 2022). "The glucagon-like peptide-1 receptor agonist family together with the renal sodium/glucose cotransporter-2 inhibitors have garnered interest as potential therapeutic agents for subjects with type 2 diabetes and obesity." (PMID 35217772, 2022). "GLP-1R agonists and SGLT2 inhibitors were found to significantly reduce the risk of major cardiovascular events in diabetes mellitus and are recommended as first-line therapies for the management of type 2 diabetes in patients at increased cardiovascular risk." (PMID 36561085, 2022). "Recently, the REWIND trial, which also used MoCA as one of the two primary endpoints, revealed that glucagon-like peptide-1 receptor agonist might reduce cognitive impairment in patients with type 2 diabetes." (PMID 35573998, 2022). "This has made the GLP-1R a therapeutic target of choice for the treatment of type 2 diabetes." (PMID 35198603, 2022). "The glucagon-like peptide-1 receptor agonists, liraglutide and semaglutide, appear to represent a first-line option in obese patients with NAFLD and type 2 diabetes mellitus (T2DM) since they induce considerable weight loss and have been extensively studied in patients with T2DM." (PMID 36120448, 2022). "Glucagon-like peptide-1 receptor (GLP-1R) agonists are being used for the treatment of type 2 diabetes (T2D) and may have beneficial effects on the pancreatic β-cells." (PMID 34575477, 2021). "Major prospective randomized clinical safety trials have demonstrated beneficial effects of treatment with glucagon-like peptide-1 receptor agonists (GLP-1RA) and sodium–glucose co-transporter-2 inhibitors (SGLT-2i) in people with type 2 diabetes and elevated cardiovascular risk." (PMID 33752680, 2021). "Similarly, GLP-1R agonism over 3 months for the treatment of type 2 diabetes improves sweet taste sensitivity and decreases preferred concentrations for a lipid emulsion." (PMID 33803053, 2021).
type 2 diabetes (continued). "Glucagon-like peptide 1 receptor agonists (GLP-1 RAs) are emerging as an important therapy to consider for patients with type 2 diabetes (T2D) given the ability of this agent class to reduce glycated haemoglobin and associated weight loss and low risk for hypoglycaemia." (PMID 33397395, 2021). "On the other hand, SGLT2 inhibitors and GLP1-R agonist was shown to be effective not only on the attenuation of GV but also on the reduction of major adverse cardiovascular events (MACE) in patients with type 2 diabetes." (PMID 34445099, 2021). "Indeed, several of the type 2 diabetes treatments target β‐cells to induce insulin secretion such as sulfonylureas, dipeptidyl peptidase 4 inhibitors (DPP4i) as well as drugs that act as GLP‐1R and GPR40 agonists." (PMID 34319011, 2021). "GLP-1R agonists are used worldwide as a major medicine to treat type 2 diabetes and obesity." (PMID 34168616, 2021). "The GLP-1R is of clinical interest not only due to its physiologic expression and functions in pancreatic islet cells and its established role in the therapy of type 2 diabetes using GLP-1 analogs, but also because of its possible role in cancer." (PMID 31951592, 2020). "Key residues for receptor binding remained in position in all of these models; therefore, E19_SS might be promising agonists for GLP‐1R and as a lead compound for type 2 diabetes mellitus." (PMID 31475422, 2020). "Current glucagon-like peptide 1 receptor (GLP-1R) agonists used in type 2 diabetes therapy." (PMID 32269764, 2020). "The recent results of Cardiovascular Outcomes Trials (CVOTs) in type 2 diabetes have clearly established the cardiovascular (CV) safety or even the benefit of two therapeutic classes, Glucagon-Like Peptide-1 receptor agonists (GLP-1 RA) and Sodium-Glucose Co-Transporter-2 inhibitors (SGLT-2i)." (PMID 32404155, 2020). "Nanodomain segregation and clustering of the glucagon-like peptide-1 receptor, a key target for type 2 diabetes therapy, is regulated by agonist binding, leading to compartmentalization of downstream signaling and clathrin-dependent internalization and impacting pancreatic beta cell responses." (PMID 31430273, 2019). "They interact with their cognate receptors (GIPR and GLP-1R), which are both members of the class B G protein-coupled receptors (GPCRs), and already recognized as targets for treatment of metabolic diseases, such as type 2 diabetes mellitus (T2DM) and obesity." (PMID 30863364, 2019). "In addition to enhancement in insulin secretion, GLP-1R agonists have also been shown to reduce proinsulin:insulin ratio (elevated in subjects with type 2 diabetes), possibly as a result of reduced ER stress and therefore, improved proinsulin processing." (PMID 29976929, 2018). "Clinical observational study also found that the expression of Glp-1R was significantly reduced in the gastric mucosa of patients with type 2 diabetes, which might contribute to impaired mucosal proliferation." (PMID 29095895, 2017). "Glucagon-like peptide-1 (Glp-1) is a gut-derived hormone belongs to the incretin family, which stimulates the release of insulin through the binding to Glp-1 receptor (Glp-1R) on pancreatic beta cells, and have been applied to the treatment of type II diabetes." (PMID 29095895, 2017). "Similarly, recent long-term studies of liraglutide and semaglutide, focusing on cardiovascular outcomes in individuals with type 2 diabetes, reveal a similar incidence of pancreatitis between groups treated with the GLP-1R agonists and placebo." (PMID 28733905, 2017). "Lixisenatide, another GLP-1R agonist, developed to treat type 2 diabetes, has been shown to have neuroprotective effects similar to liraglutide, including improved working memory, increased LTP, decreased Aβ deposition, and reduced inflammatory responses in an AD mouse model." (PMID 28846606, 2017).
type 2 diabetes (continued). "Lowering of blood pressure has been observed in subjects with type 2 diabetes receiving long-term treatment with GLP-1 receptor (GLP-1R) agonists, although the mechanisms underlying this are not fully understood." (PMID 26759609, 2016). "Several GLP-1R agonists have been used to treat type-II diabetes." (PMID 26988916, 2016). "Exendin-4 (EXD-4), a glucagon-like peptide-1 receptor agonist used for the treatment of type 2 diabetes, and human insulin-like growth factor type 1 (hIGF-1), which is used to treat type 1 and 2 diabetes were expressed under fusion with or without HL28 peptide." (PMID 27412460, 2016). "Incretin-based therapies in patients with type 2 diabetes mellitus by using either the injection form of glucagon-like peptide-1 receptor (GLP-1R) agonists or the oral form of dipeptidyl peptidase-4 (DPP-4) inhibitors have been shown to increase the risk of thyroid cancer." (PMID 27029076, 2016). "Furthermore, as we have previously shown using GLP-1R agonist exendin-4, vildagliptin decreased the oxidative stress in the kidney of rat model of type 2 diabetes." (PMID 26881236, 2016). "Thus, glucagon-like peptide-1-based therapies (glucagon-like peptide-1 receptor agonists and dipeptidyl peptidase-4 inhibitors) are now well accepted in the management of type 2 diabetes." (PMID 26366173, 2015). "Drugs targeting the GLP-1R system are already widely prescribed for their incretin properties to treat type 2 diabetes, but they may be useful in a wider context related to energy balance." (PMID 26254578, 2015). "GLP1R agonists represent a promising group of incretin-based therapeutics for type 2 diabetes." (PMID 25890210, 2015). "Interestingly, GLP1R expression is decreased in pancreatic islets from patients with type 2 diabetes and hyperglycaemic rats." (PMID 23879380, 2013). "Exendin-4 is a long-acting glucagon-like peptide-1 receptor agonist approved for the treatment of type 2 diabetes mellitus that not only effectively induces glucose-dependent insulin secretion to regulate blood glucose levels but also reduces apoptotic cell death of pancreatic β-cells." (PMID 24312624, 2013). "Post hoc analyses of phase III studies of patients with type 2 diabetes treated with exenatide(bid or qw) or liraglutide(qd) showed that these GLP-1R agonists reduced blood pressure, an effect largely independent of weight loss, and that liraglutide slightly increased heart rate." (PMID 21167014, 2012). "Given its physiological roles, the GLP-1R is targeted for treatment of type 2 diabetes." (PMID 23094100, 2012). "GLP-1R activation also promotes preservation and expansion of beta-cell mass in type 2 diabetic rodent models through protecting beta cells against the deleterious effects of the diabetic milieu (i.e., increased cytokine toxicity, glucose toxicity, and lipotoxicity)." (PMID 21716694, 2011). "Glucagon-like peptide-1 receptor agonists (GLP-1RAs) have revolutionized the management of type 2 diabetes mellitus (T2DM) by providing robust glycemic control alongside significant cardioprotective and renoprotective benefits." (PMID 42193383, 2026). "In the last decade, we have learnt of the cardiorenal benefits of sodium-glucose cotransporter 2 inhibitors (SGLT2i) and glucagon-like peptide-1 receptor agonists (GLP-1RA) in people with type 2 diabetes (T2D)." (PMID 40588647, 2025). "Among these, glucagon-like peptide-1 receptor agonists (GLP-1RAs)—originally developed for glycemic control in type 2 diabetes mellitus (T2DM)—have gained relevance." (PMID 40869417, 2025). "Incretin-based agents such as glucagon-like peptide-1 receptor agonists (GLP-1 RA) represent a new class of AOMs that were initially used to treat type 2 diabetes mellitus (T2DM)." (PMID 41328178, 2025). "Glucagon-like peptide 1 receptor agonists (GLP-1RAs) are medications commonly used for patients with type 2 diabetes mellitus (T2DM) and obesity." (PMID 39971882, 2025).